STAT3 (signal transducer and activator of transcription 3)
Diseases named in the same sentence as STAT3 in open-access papers (continued):
Sharing a sentence is not in itself a finding about the gene and the disease.
cancer (continued). "Resveratrol has been shown to inhibit the activation of JAK2-STAT3, Src-STAT3, AKT and IKK-NFκB pathways and to induce apoptosis in several cancer cell lines." (PMID 21209944, 2010). "The signal transducer and activator of transcription 3 (STAT-3) is frequently overexpressed in cancer cells, propagates tumorigenesis, and is a key regulator of immune suppression in cancer patients." (PMID 19900287, 2009). "AP-1, STAT3, and EGR1 are considered important transcription factors that are involved in regulating gene expression in human cancers, including HNSCCs." (PMID 17498291, 2007). "The treatment induced the expression of LIFRα and established a LIF-dependent STAT3 and ERK signaling that was comparable to the level observed in the carcinoma cells." (PMID 16271139, 2005). "The pair-wise comparison also revealed that 5/23 of the abnormal cases (4 metaplasia and 1 carcinoma) had a LIF response detectable by the activation of ERK and STAT3." (PMID 16271139, 2005). "Here, we review the mechanistic basis and clinical correlations of STAT3 p-S727 across cancers with emphasis on TNBC, and discuss how compartmentalized STAT3 pools may integrate kinase signaling, nutrient sensing, and stress responses." (PMID 41828466, 2026). "STAT3, a well-established oncogenic transcription factor, is frequently activated in PDAC and plays critical roles in cell proliferation, invasion, immune evasion, and cancer stemness." (PMID 40856537, 2026). "Additionally, targeting key components of IL-6 signaling, such as IL-6Rs, gp130, STAT3, and JAK, with monoclonal antibodies, remains a major challenge in preclinical cancer research." (PMID 41596531, 2026). "STAT3 and AKT1 consistently emerged as common top-scoring hub genes in both cancers." (PMID 41829818, 2026). "Although the GO and KEGG results showed that the predicted FImRNAs are mainly enriched in cell cycle and proliferation, based on multiple studies, these genes improve cancer cell growth through activation of signaling pathways like Wnt, PI3K/Akt, STAT3, and MAPK pathways." (PMID 41568058, 2026). "STAT3 and STAT5 are central to cancer-related inflammation and immunity." (PMID 41057685, 2026). "What is more, silencing B7-H3 expression has been found to enhance the sensitivity of cancer cells to mTOR inhibitors and paclitaxel by disrupting the JAK2/STAT3 signaling pathway, while B7-H3-induced activation of the Raf/MEK/ERK signaling has been implicated in promoting lung metastasis." (PMID 40801642, 2025). "Initially, we analyzed data of the TCGA database to assess the expression profiles of STAT3 across various malignant tumors, comparing these with non-pathological tissue expression values from the GTEx database." (PMID 40265014, 2025). "The interplay between these immune cells and the major pathways involved (NF-κB and STAT3) suggests that disrupting the TME and suppressing cancer progression may require a multimodal approach that involves immunomodulatory drugs as well as pathway inhibitors." (PMID 40407951, 2025). "Along with the functions of MSN as a phosphate messenger between LPAR1 and GTPase, we found additional novel features of MSN as an intracellular transporter that transports STAT3 into the nuclei of TNBC cells, which is crucial for the transcription of specific genes in cancer." (PMID 40696387, 2025). "The downstream targets of STAT3 include anti-apoptotic genes (BCL-2, BCL-XL, MCL-1), cell survival pathway genes (Cyclin-D1, Survivin), drug efflux (MDR1), and maintenance genes of cancer stem cells (CD133)." (PMID 40149331, 2025).
cancer (continued). "Given the known role of the IL-6/STAT3 pathway in enhancing cancer cell stemness, it was of interest to explore whether CD109-mediated IL6Rα/STAT3 pathway activation leads to increased stemness." (PMID 40317079, 2025). "Additionally, M2 macrophage and MDSCs secrete cytokines like IL-6 and IL-11, which activate STAT3 and create a signalling loop that fosters a TME favourable for cancer cells." (PMID 40407951, 2025). "Further, the exploration of valine–niclosamide’s activity against NF-kB, STAT3, KRAS, and other oncogenic pathways that demonstrate rebound activity following AR-KO is necessary in HCC, PCa, and other cancers to demonstrate the maintenance of key types of activity across cancer types." (PMID 40805231, 2025). "Secondly, while we demonstrated that Lyc.HCL inhibits cancer cell growth, metastasis, and invasiveness by targeting TRIM22 and modulating the JAK2/STAT3 and ERK pathways in vitro and in vivo, our in vivo experiments were limited to a subcutaneous xenograft model." (PMID 40075566, 2025). "Because STAT3 is activated upon FER expression and MAPK1 has been identified as a direct FER substrate, FER is likely a multifactorial driver of invasive cancer growth." (PMID 41115375, 2025). "STAT3 is usually activated by IL-6 family cytokines via JAK and is involved in multiple cellular pathways, which in turn affects the proliferation, progression and immune dysfunction of cancer cells." (PMID 40433378, 2025). "In BTC, STAT3 overexpression has been associated with worse pathological characteristics, as well as negative surgical outcomes, and some data identified STAT3 as a driver of cancer proliferation and metastasis." (PMID 40426911, 2025). "HnRNPs participate in cancer-related pathways including DNA repair and IL6/JAK/STAT3 signaling." (PMID 39868801, 2025). "Activation of TKT by STAT3 may drive metabolic reprogramming by enhancing the flow of glucose in the PPP, thereby enhancing cancer cell survival and proliferation." (PMID 40230848, 2025). "Additionally, future studies investigating how FXR modulates SOCS3 and consequently impacts STAT3 signaling in CSCs could facilitate the development of more effective treatments aimed at disrupting the CSCs, ultimately improving patient outcomes across various cancer types." (PMID 39940889, 2025). "RBM47 is repressed by several EMT-related transcription factors, such as snail family transcriptional repressor 1 (SNAIL), snail family transcriptional repressor 2 (SLUG), signal transducer and activator of transcription 3 (STAT3), and SMAD family member 3 (SMAD3) in cancer cells." (PMID 41335176, 2025). "Moreover, genes related to cancer therapeutic targets, such as ABCG2, GSK3B, PTCH1, STAT3 and WEE1, were also upregulated." (PMID 39726234, 2025). "Many JAK inhibitors displaying clinical efficacy have been and are being developed, though there are currently no approved drugs that selectively target STAT3 in the field of cancer treatment." (PMID 41463071, 2025). "IL-6-driven STAT3 signaling may also promote LAG-3 expression, as shown in cancer patient-derived naïve CD8 T cells." (PMID 39981237, 2025). "Activation of the p38 MAPK and JAK2/STAT3 signaling pathways have both been reported to increase the expression level of COX-2 in cancers, suggesting that UPF1 might regulate COX-2 expression by activating the p38 MAPK and JAK2/STAT3 pathways." (PMID 41293174, 2025). "Additionally, MCPIP1 inhibits cancer stemness and mixed EMT of PC cells by suppressing the IL6/JAK2/STAT3 axis." (PMID 40874680, 2025). "In cancer progression, STAT3 mainly promotes oncogenic transcription through well‐established phosphorylation‐dependent pathways, such as the JAK/STAT3 or IL‐6/STAT3 axes, which upregulate cyclin D1, Bcl‐xL and survivin." (PMID 40464702, 2025).
cancer (continued). "For instance, if genes responsive to U-STAT3 are expressed in certain cancers while those responsive to STAT3 dimers are not, it would suggest that STAT3 overexpression in these cases is triggered by a signal distinct from STAT3 dimers." (PMID 40725945, 2025). "STAT3 (Signal Transducer and Activator of Transcription 3), which contains an SH2 domain, plays a pivotal role in cancer progression and immune evasion because it facilitates the dimerization of STAT3, which is essential for their activation and subsequent nuclear translocation." (PMID 39786519, 2025). "Together, these data demonstrate that efficient knockdown of neutrophil STAT3 via the intratumoral injection of CpG-Stat3ASO supported the expansion of potently cytotoxic CD8+ T cells and therefore provides a promising strategy for cancer immunotherapy." (PMID 40885734, 2025). "Therefore, in this study, we selected STAT3, NF-κB, SOD, VEGF, and MMP9 due to their established involvement in cancer-related pathways such as inflammation, oxidative stress, angiogenesis, and metastasis." (PMID 41326479, 2025). "The possible apoptotic pathways for anti-cancer effects of curcumin on cell signal transduction include PI3K, Akt, mTOR, ERK5, AP-1, TGF-β, Wnt, β-catenin, Shh, PAK1, Rac1, STAT3, PPARγ, EBPα, NLRP3 inflammasome, p38MAPK, Nrf2, Notch-1, AMPK, TLR-4, and MyD-88." (PMID 41149437, 2025). "Furthermore, paeonol inhibits cancer cell growth, proliferation, invasion and metastasis by inducing cell apoptosis and the suppression of the TLR4/NF-κB/STAT3/MAPK/PI3K/AKT/CHOP/VEGF/HIF-1α, pathways." (PMID 40083771, 2025). "Niclosamide, a specific inhibitor of STAT3, can negate the upregulation of MRP1 and MDR1 induced by MALAT1, highlighting the potential of targeting STAT3 to modulate drug resistance mediated by lncRNAs in cancer therapy." (PMID 41276852, 2025). "Results showed that DHA effectively suppresses cancer stem cell‐like properties and significantly inhibits invasion and migration by regulating the JAK2/STAT3 signaling pathway and reducing the phosphorylation of JAK2 and STAT3." (PMID 41231037, 2025). "Conclusively, STAT3 seems to be one of the major downstream effectors of BCP in regulating a complex network, including NF-κB and PI3K/AKT/mTOR and other cell cycle and apoptosis regulatory molecules in cancer." (PMID 40333803, 2025). "Exogenous stimulation of cancer cells with eNAMPT in the absence of enzyme substrates has been shown to activate specific intracellular signaling pathways, such as STAT3, NF-κB, Akt, and p38, within minutes." (PMID 40083697, 2025). "According to the results of GSEA in pan-cancer, NCBP2 was closely related to immune related pathways, such as IFN-alpha response, IFN-gamma response, IL-6/JAK/STAT3 signaling, IL-2/STAT5 signaling, allograft-rejection pathways, inflammatory response, and TNF alpha signaling-via NFKB." (PMID 40124611, 2025). "They found that curcumin inhibited the secretion of IL‐6 and interleukin‐8 (IL‐8), phosphorylation of signal transducer and activator of transcription 3 (STAT3), and the co‐immunoprecipitation of phospho‐STAT3 with phospho‐focal adhesion kinase 397 (FAK397), thereby impeding cancer cell motility." (PMID 41323836, 2025). "Notably, the upregulation of PAR-2 has been shown to attenuate the cytotoxic efficacy of chemotherapeutic agents by activating STAT3 and MAPK pathways, both of which promote survival and reduce apoptosis in cancer cells." (PMID 40564985, 2025). "Although p-STAT3 was reported to act as a predictive biomarker of BBI608’s clinical activity in cancer patients, it failed to predict the clinical activity in some studies." (PMID 40075071, 2025).
cancer (continued). "Although targeting other proteins that play roles in centrosome clustering can induce multipolar spindles and reduce cancer cell growth, such as Hsp72, Nek6 or STAT3, no therapeutic approaches have yet reached clinical trials." (PMID 39789388, 2025). "STAT3 contributes significantly to survival and proliferation of EBV+ cancer/transformed cells." (PMID 40354417, 2025). "Despite not yet being used in clinical practice, several STAT3 inhibitors have demonstrated a reduction of malignant phenotypes in different cancer types, with AZD9150 and TTI‐101 (formerly C188‐9) showing promising therapeutic efficacy in clinical trials." (PMID 40808640, 2025). "We found that the expression of p-STAT3 was significantly elevated in CAF compared with “PAF” (para-cancer fibroblasts) (data not shown)." (PMID 40703348, 2025). "Furthermore, the signal transducer and activator of transcription 3 (STAT3) functions as a transcription factor and signal mediator in cancer and inflammation." (PMID 40689208, 2025). "The signal transducer and activator of transcription (STAT) proteins family, comprising STAT1, STAT2, STAT3, STAT4, STAT5a, STAT5b and STAT6, mediates multiple intracellular signaling pathways and influences the initiation of malignant transformation and cancer progression." (PMID 40303303, 2025). "Furthermore, numerous studies have reported that TREM2 acts as an oncogene, advancing cancer by triggering the PI3K/AKT and JAK/STAT3 pathways." (PMID 40670983, 2025). "However, resveratrol is also a known inhibitor of various other pathways, such as STAT3, PI3K, AKT, mTOR, and NF-kB pathways that inhibit cancer progression, which is why it has been used in cancer research." (PMID 40563757, 2025). "This aligns with reports that STAT3 represses SLC7A11/GPX4 in non-malignant settings but promotes ferroptosis resistance in cancer." (PMID 41515376, 2025). "Additionally, the drug has shown the ability to modulate STAT3, EGFR, and other crucial pathways across multiple cancer types." (PMID 41155573, 2025). "In pancreatic cancer, under IL-6 stimulation, the cancer cells release exosomal FGD5-AS1, which is taken up by macrophages, where it can recruit p300 to promote STAT3-K685 acetylation, activate the STAT3/NF-κB signaling pathway, and mediate M2 polarization of macrophages." (PMID 40612677, 2025). "However, excessive signalling based on these factors, mainly STAT3 and STAT5, has been noted in different cancers." (PMID 40729003, 2025). "Taken together, our study shows that targeting solely neutrophil STAT3 with strategies such as CpG-STAT3ASO could provide an efficient and clinically relevant therapeutic strategy to maximize treatment efficacy in cancer." (PMID 40885734, 2025). "In addition, there is evidence that STAT3 activation can lead to MCP-1 overexpression in some tumors, creating a positive feedback loop, thereby facilitating cancer progression." (PMID 40426911, 2025). "The activation of STAT3 and NF-κB signaling pathways by pro-inflammatory cytokines triggers the expression of the c-myc oncogene and MMP13, which subsequently contributes to EMT, persistent inflammation, and, ultimately, cancer development." (PMID 40497987, 2025). "Furthermore, cytokines or inflammatory factors secreted by cancer cells and stromal cells shall induce CAF activation by stimulating STAT3 activation." (PMID 40703348, 2025). "Using the JAK pathway inhibitor ruxolitinib to inhibit IL6/STAT3 signaling disrupts the ER-FOXA1-pSTAT3 enhancer-driven transcriptional program of target genes in breast cancer and suppresses the invasive capacity of cancer cells." (PMID 40032852, 2025). "Although it has been demonstrated that STAT3 is linked to the poor prognosis and treatment outcomes of various cancer types, STAT3-targeted therapy has not yet been approved for clinical use." (PMID 39944829, 2025).
cancer (continued). "By targeting TRIM22 and modulating the JAK2/STAT3 and ERK signaling pathways, Lyc.HCL may offer a promising strategy for the treatment of ESCC and other cancers in which TRIM22 plays a significant role." (PMID 40075566, 2025). "Additionally, apoptosis in human cancer cells is induced by various platinum (IV) compounds, including CPA‐1, CPA‐7, and platinum (IV) tetrachloride, which inhibit STAT3 DNA binding." (PMID 40166646, 2025). "We have previously shown that cancer stem cells are more sensitive to the inhibition of STAT3-driven ALDH activity upon radiation than their non-stem cell components." (PMID 40076923, 2025). "circHIPK3/miR-124-3p/miR-637/miR-338-3p are the most well documented interactions in cancers that may control MAPK, Jak/STAT3, Wnt/β-catenin, and PI3K/Akt signaling pathways." (PMID 40061896, 2025). "Non-canonical STAT3 signaling, while less understood, has received particular attention because of its involvement in cancer." (PMID 40420174, 2025). "Such as, PRMT6 asymmetrically di-methylates STAT3 at arginine-729 (R729) and this modification is essential for membrane localization of STAT3, interaction with JAK2, phosphorylation of STAT3 Y705, and PRMT6-driven cancer cell metastasis." (PMID 40164592, 2025). "Furthermore, extracellular vesicles derived from macrophages were shown to activate STAT3 phosphorylation by downregulating MISP, thereby promoting therapeutic resistance in cancer cells." (PMID 40428339, 2025). "Since the p38 MAPK and JAK2/STAT3 signaling pathways are known to be upstream regulators of COX-2 in cancer cells, the activation of the ERK/MAPK and JAK2/STAT3 pathways by COX-2 may form a positive feedback loop to promote the survival of NPC cells." (PMID 41293174, 2025). "Beyond radiation resistance, HFDs promote cancer cell survival through obesity-driven hyperinsulinemia and chronic inflammation, which activate oncogenic pro-survival pathways, including PI3K/AKT and STAT3." (PMID 40282189, 2025). "For example, targeting STAT3 phosphorylation in mouse neutrophils supported the ability of these cells to stimulate CD8+ T cells, the same phenomenon we observed in neutrophils derived from cancer patients." (PMID 40885734, 2025). "miR-142-3p targets the tumor suppressor FOXO1, promoting proliferation, and miR-4449 may influence STAT3 signaling by targeting SOCS3, as suggested in other cancers." (PMID 41462933, 2025). "Among these, STAT3 is regularly supported in the literature as essential for S100A8/A9 expression in both cancer and immune cells, and C/EBPβ has also been shown to control S100A8/A9 expression in a cancer cell model." (PMID 38378783, 2024). "Furthermore, through the JAK2/STAT3 and SHP2/Grb2/PI3K/AKT signaling pathways, cancer cell anoikis resistance, invasion, and EMT were promoted by decreased SH2B3 and elevated TGF-β in LC." (PMID 39547513, 2024). "STAT3, a member of the STAT protein family, is a transcription factor that extensively participates in the regulation of acute and chronic inflammation, autoimmunity, metabolism, development and cancer progression." (PMID 39218978, 2024). "In this context, methylation of STAT3 by PRMT5 can promote activated tyrosine phosphorylation of STAT3, which may work to maintain continuous STAT3 activation in cancer cells." (PMID 38760429, 2024). "Moreover, KTN inhibited cancer cell migration by suppressing metastasis-related protein expression and EMT via STAT3 downregulation." (PMID 39519023, 2024). "To determine whether MUC1 plays a role in STAT3’s sensitivity to Napabucasin, we treated the panel of low and high MUC1 expressing cancer cells with increasing concentrations of Napabucasin." (PMID 38326371, 2024). "Based on evidence, IL-6/STAT3 (signal transducer and activator of transcription-3) signaling and integrin-focal adhesion signaling are other known signaling pathways involved in the regulation of both EMT and autophagy processes in cancer." (PMID 38398197, 2024).